SSBP1 (single stranded DNA binding protein 1)
Diseases named in the same sentence as SSBP1 in open-access papers (continued):
Sharing a sentence is not in itself a finding about the gene and the disease.
HCMV infection (1 paper, 2017). "The results of western blot also showed that HCMV infection inhibited the expression of SSBP1 from 24 to 96 h, indicating that HCMV infection down-regulated SSBP1 in a time-dependent manner." (PMID 28902926, 2017). "The expression levels of SSBP1 mRNA and protein after HCMV infection were significantly down-regulated." (PMID 28902926, 2017). "The results showed that the inhibition of SSBP1 by HCMV infection promotes lipid accumulation in the cells." (PMID 28902926, 2017). "We screened the differential expression of mRNAs after HCMV infection by suppression subtractive hybridization and the expression levels of SSBP1 mRNA and protein after HCMV infection by real-time PCR and western blot." (PMID 28902926, 2017). "Real time PCR was used to evaluate the SSBP1 expression after HCMV infection." (PMID 28902926, 2017).
Hepatic steatosis (1 paper, 2022). Steatosis is a term used to denote lipid accumulation within hepatocytes. "Additionally, peripheral blood leukocyte ACSL4, CRLS1, CTP1A, SIGIRR, SSBP1, and ZNF622 genes containing DMPs might be used as serum biomarkers to stratify NAFLD patients into groups with simple hepatic steatosis and NASH." (PMID 35433752, 2022).
hepatocellular carcinoma (1 paper, 2017). A malignant tumor that arises from hepatocytes. "In contrast, SSBP1 expression is dramatically increased in hepatocellular carcinoma (HCC) and associated with poor prognosis." (PMID 29340022, 2017).
invasive breast carcinoma (1 paper, 2020). A carcinoma that infiltrates the breast parenchyma. "Genes specifically differentially methylated in invasive breast cancer, UCP2 and SSBP1, show no change in gene expression in DCIS but significant change in gene expression in invasive breast cancer tissue from human clinical samples." (PMID 32051475, 2020).
mtDNA depletion syndrome (1 paper, 2024). "In the literature, 10 studies have identified 13 distinct missense mutations in SSBP1, all of which are associated with mtDNA depletion syndrome." (PMID 39104869, 2024).
neuroblastoma (1 paper, 2012). Neuroblastoma (NB) is the most common solid, extracranial childhood tumor. "We identified six genes (DLGAP5, DSCC1, SMO, SNRPD1, SSBP1, and UBE2C) with a vital role in mitosis and these are promising therapeutic targets for neuroblastoma." (PMID 23251412, 2012).
Obesity (1 paper, 2017). Accumulation of substantial excess body fat. "Moreover, it has been reported that down-regulation of SSBP1 is associated with creating a metabolic state that leads to the development of obesity, and SSBP1 has also been identified to promote lipid accumulation in liver." (PMID 28902926, 2017).
Pearson syndrome (1 paper, 2020). Pearson syndrome is characterized by refractory sideroblastic anemia, vacuolization of bone marrow precursors and exocrine pancreatic dysfunction. "Nevertheless, a de novo nuclear mutation in SSBP1, was recently discovered to cause SLSMD in patients with KSS Spectrum or Pearson Syndrome phenotypes." (PMID 33105723, 2020).
serous ovarian cancer (1 paper, 2010). "That is, one group including: SSBP1, IFI6 DDT, IFI27, C11orf92, NFKBIA, TNXB, NEAT1 and TFG, was up-regulated in most patients with stage III serous ovarian cancer." (PMID 20969748, 2010).
thyroid cancer (1 paper, 2024). "NHEJ- (XRCC6, XRCC5, PRKDC) and HR‐ (SSBP1, SEM1, RPA2, RPA3)-related genes were found to be expressed in both normal follicular and thyroid cancer cells." (PMID 38380364, 2024). "NHEJ- (XRCC6, XRCC5, PRKDC) and HR- (SSBP1, SEM1, RPA2, RPA3) related genes are expressed by both normal follicular and thyroid cancer cells." (PMID 38380364, 2024).
viral infection (1 paper, 2015). "The localization of SSBP1 has been thought to be mitochondrial under physiological conditions, and viral infection was suggested to induce the nuclear translocation of SSBP1." (PMID 25762445, 2015).
Visual impairment (1 paper, 2021). "SSBP1-related DOA shares similarities with OPA1-related DOA with an incomplete penetrance and an early childhood visual impairment." (PMID 34548540, 2021).
cancer (11 papers, 2012 to 2025). A tumor composed of atypical neoplastic, often pleomorphic cells that invade other tissues. "It is therefore highly plausible that rs6976500 G allele genotype enhance the sensitivity of cancer cells to chemotherapy agents maybe through down-regulating SSBP1 expression." (PMID 29340022, 2017). "And additional research is required to clarify the regulatory relationships and underlying mechanisms of SSBP1, RPA3 and TUBB2A in Cancer cell lactylation despite demonstrating an association between them." (PMID 40642071, 2025). "Recently, an increasing number of studies have demonstrated that SSBP1 is significantly correlated with poor patient prognosis and is involved in tumorigenesis, proliferation, and drug sensitivity in certain human cancers." (PMID 36180956, 2022). "Conversely, multiple studies have demonstrated that SSBP1 is vnvolved in various human cancers and plays an important role." (PMID 36180956, 2022). "In this study, we demonstrated that SSBP1 knockdown promotes ROS production and alters MMP in GBM cells, which is consistent with the results of SSBP1 knockdown in other cancers." (PMID 36180956, 2022). "SSBP1 is a housekeeping gene involved also in mitochondrial biogenesis and it has been shown to regulate mitochondrial mass in cancer states." (PMID 33634182, 2021). "Consistently, a number of scientific studies have suggested that aberrant SSBP1 expression is correlated to the aggressive phenotype and poor survival of human cancers." (PMID 29340022, 2017). "Recently, aberrant expression of SSBP1 has been frequently reported in many cancers, suggesting a possible functional link between SSBP1 and human cancer." (PMID 29340022, 2017). "Knockdown of SSBP1 leads to a decrease in mitochondrial content, suggesting that SSBP1 may promote cancer progression by influencing mitochondrial biogenesis." (PMID 35180892, 2022). "The evidence indicating that SSBP1 can play either a procancer or anticancer role in different types of cancer suggests that further exploration of the function of SSBP1 in cancer development could deepen our understanding of cancer." (PMID 35180892, 2022). "Moreover, in non-small-cell lung cancer, SSBP1 enhances the resistance of cancer cells to ionizing radiation by inhibiting apoptosis." (PMID 35180892, 2022). "Therefore, SSBP1 are regarded as a promising prognostic marker and an therapeutic target for human cancer." (PMID 29340022, 2017). "Despite the widely investigations of SSBP1 expression on cancer evolution, however, there was no study investigating the effect of SSBP1 gene polymorphisms on GC prognosis or ACT treatment response." (PMID 29340022, 2017). "The proportion of SSBP1, RPA3, and TUBB2A cancer cells increased synchronously during the quasi-time course." (PMID 40642071, 2025). "We divided cancer cells into six groups: SSBP1+ cancer group, SSBP1− cancer group, RPA3+ cancer group and RPA3− cancer group, TUBB2A+ cancer group and TUBB2A− cancer group." (PMID 40642071, 2025). "In the end, we identified six genes (DLGAP5, DSCC1, SSBP1, UBE2C, SNRPD1, and SMO) with a vital role in prevention of cell death in both cell lines and hence six potential drug targets for silencing in cancer therapy." (PMID 23251412, 2012). "In addition, this is the first study showing the effects of this binding domain on genes involved in cancer, such as STMN1 or SSBP1, which are not direct targets of RUNX2." (PMID 30463392, 2018).
infection (7 papers, 2013 to 2025). The state of being infected such as from the introduction of a foreign agent such as serum, vaccine, antigenic substance or organism. "The results showed that from 24 to 96 h post-infection, in SSBP1 over-expressed cells, the total cholesterol contents were significantly lower than those of control." (PMID 28902926, 2017). "Single-stranded DNA-binding protein (SSBP1) has a key role in binding with single strand DNA and repairing DNA wound during stress and infection." (PMID 28902926, 2017). "The results showed that SSBP1 gene expression was significantly down-regulated from 24 to 96 h after infection in a time-dependent manner when compared with mock-infection group." (PMID 28902926, 2017). "The results revealed that 48 h after infection with B. abortus A19, the mRNA expression of mtDNA2-6, POLG, SSBP1, and TOP1 in the BTC group was significantly greater than that in the control group." (PMID 40317067, 2025). "Infection with E. coli increased expression of polymerase gamma (POLG), single-stranded DNA-binding protein (SSBP1), TWINKLE (TWNK), and DNA topoisomerase 1 (TOP1) genes." (PMID 36430657, 2022). "The objective of this study was to observe the infection of human cytomegalovirus (HCMV) to human umbilical vein endothelial cells, and its effect on the expression of single-stranded DNA-binding protein (SSBP1) and on lipid metabolism in endothelial cells." (PMID 28902926, 2017). "Therefore, in this study, we aimed to observe the infection of HCMV in human umbilical vein endothelial cells (HUVECs), and its effect on the expression of SSBP1 and on lipid metabolism in endothelial cells." (PMID 28902926, 2017).
mitochondrial disease (7 papers, 2019 to 2025). "Since 2018, over 10 mutations have been identified in the SSBP1 gene that have been associated with mitochondrial diseases." (PMID 41226312, 2025). "In 2019, a single de novo SSBP1 mutation (E27K) was observed in a 14-year-old patient who had mitochondrial disease manifestations across the full Pearson, Kearns–Sayre, and Leigh syndromes spectrum." (PMID 41226312, 2025). "In summary, we identified a novel SSBP1 mutation and its causal relationship to mitochondrial disease." (PMID 39104869, 2024). "Taken together, base editing-based gene therapies may be a promising treatment for mitochondrial diseases, including those associated with SSBP1 mutations." (PMID 39104869, 2024). "This study corrected a disease-causing SSBP1 mutation, essential for mitochondrial replication, using a specialized base editor designed to minimize off-target effects, accelerating clinical applications for mitochondrial diseases." (PMID 39104869, 2024). "As sequencing technology for clinical diagnosis expands and improves for mitochondrial disease patients, awareness of this patch and its constituent residues may help to identify additional SSBP1 variants." (PMID 31479473, 2019). "With the exception of SSBP1, a key component of the mitochondrial replication fork, to date, all nuclear genes directly involved in mtDNA replication (POLG, POLG2, TWINKLE, RNASEH1, DNA2, MGME1) have been associated with mitochondrial disease, mtDNA depletion, and/or mtDNA deletion." (PMID 31550237, 2020).
tumor (5 papers, 2004 to 2024). "ERVmap-k48 used as a control has a sequence of approximately 3900 bp encoding for Gag and is located near the housekeeping gene SSBP1, which has been hypothesized to drive its transcription and possibly explains the reason for stable levels in normal versus tumor tissue." (PMID 36467966, 2022). "Furthermore, we demonstrated that the downregulation of SSBP1 in GBM suppresses tumor proliferation and results in mitochondrial dysfunction." (PMID 36180956, 2022). "Additionally, in complex with SSBP1, CSK2 is conjected to take part in mitochondrial DNA (mtDNA) replication, accelerating tumor invasion." (PMID 38462627, 2024).
genetic disorders (2 papers, 2023). "Although parental mosaicism has been reported in different genetic disorders, parental mosaicism in SSBP1 has not been reported before." (PMID 36993412, 2023).
autosomal recessive disease (1 paper, 2021). Autosomal recessive form of disease. "This revealed a single rare variant, c.394A>G p.(Ile132Val), that has been reported previously in SSBP1-associated autosomal recessive disease." (PMID 34905022, 2021).
SSBP1 also shares sentences with these, for which no sentence is quoted: scrapie (5 papers); Headache (2); Alzheimer disease (1); anhidrosis (1); Atrophy (1); autism (1); bipolar disorder (1); cervical tumor (1); glioblastoma (1); hereditary optic neuropathies (1); invasive carcinoma (1); kidney failure (1); migraine (1); Mitochondrial myopathy (1); Nephropathy (1); optic neuropathies (1); Rod-cone dystrophy (1).